MTDH (metadherin)
Diseases named in the same sentence as MTDH in open-access papers (continued):
Sharing a sentence is not in itself a finding about the gene and the disease.
breast carcinoma (continued). "That study showed that overexpression of miR-375 increased sensitivity of TAM-R MCF-7 cells to TAM by decreasing the expression of metadherin (MTDH) which induces EMT in breast cancer cells." (PMID 23626803, 2013). "Hu and his colleague found that MTDH gene was over-expressed in more than 40% of breast cancer patients, which not only promoted the metastasis of tumor cells, but also enhanced the resistance to chemotherapy drugs and affected the clinical therapeutic effect." (PMID 23984913, 2013). "Gene copy number gain of CCND1, TRAF4, CDC6 and MTDH was seen in >40 % of the male breast cancer cases, with also frequent amplification." (PMID 22527098, 2012). "In conclusion, copy number gain of the genes CCND1 (11q13), TRAF4 (17q11), CDC6 (17q21), and MTDH (8q22) is very common in male breast cancer (>40 %) and these genes probably play a role in male breast carcinogenesis." (PMID 22527098, 2012). "Copy number gain in the genes MED1 (p < 0.001), BIRC5 (p < 0.001), PRDM14 (p = 0.003), and MTDH (p = 0.003) were significantly correlated with high grade male breast cancer." (PMID 22527098, 2012). "This change demonstrated that elevated MTDH expression was required for LPS-induced breast cancer cell migration." (PMID 22195048, 2011). "Recently we found that MTDH enhanced EMT which drove the aggressive behavior of the breast cancer and identified novel SNPs of MTDH that are correlated to breast cancer susceptibility." (PMID 22195048, 2011). "This indicated that MTDH increased the metastatic ability of breast cancer via the secretion of these cytokines." (PMID 22195048, 2011). "The expression of MTDH has been detected in melanoma, glioma, neuroblastoma, and carcinomas of breast, prostate, liver, kidney, colorectum and esophagus." (PMID 22195048, 2011). "To date, we are the first to show the role of MTDH in the TLR4 signaling pathway in breast cancer cell line, MDA-MB-231 cells." (PMID 22195048, 2011). "We show that the pro-inflammatory endotoxin Lipopolysaccharide (LPS) upregulates the expression of Metadherin (MTDH), a recently identified oncogene, in a number of breast cancer lines." (PMID 22195048, 2011). "Over-expression of MTDH correlates with poor clinical outcome in breast cancer, neuroblastoma, hepatocellular carcinoma and prostate cancer." (PMID 21687633, 2011). "Our group has also previously published on MTDH, using computational algorithms to establish the overexpression of MTDH in breast cancer." (PMID 21408129, 2011). "Here we determined the function of MTDH in promoting tumor progression in response to LPS and investigated how LPS regulated MTDH expression in breast cancer cells." (PMID 22195048, 2011). "MTDH has been also found to be upregulated in several types of human cancers, including breast cancer, prostate cancer, glioblastoma, hepatocellular carcinoma and esophageal carcinoma." (PMID 20565850, 2010). "Of note, MTDH activation by 8q22 genomic gain promotes chemoresistance and metastasis of poor-prognosis breast cancer." (PMID 20584321, 2010). "Upregulation of MTDH increased lung metastasis of breast cancer cell, as well as migration and invasion of glioma cells." (PMID 20565850, 2010). "For example, a previous study using gene expression to identify segmental aneuploidy had identified MTDH as candidate oncogene in 8q22 amplified (factor 35) in a small region in breast cancers." (PMID 20824128, 2010). "In the present study, we focused on elucidating the role of MTDH in the progression of precancerous lesions to breast cancer." (PMID 20565850, 2010). "Based on this, we considered whether S-palmitoylation of MTDH influence ferroptosis sensitivity in breast cancer cells." (PMID 41318030, 2025).
breast carcinoma (continued). "Previous studies have reported that MTDH interacts with SND1 to promote breast cancer progression." (PMID 40775338, 2025). "Also, we found that the lipid droplet numbers were significantly reduced in MTDH knockdown cells compared with control cells, suggesting that MTDH regulates TG level in breast cancer cells." (PMID 41318030, 2025). "Subsequently, we attempt to understand whether the S-palmitoylation of MTDH is relevant for breast cancer cells migration." (PMID 41318030, 2025). "Collectively, our results highlight the crucial role of MTDH S-palmitoylation in modulating protein interactions and ferroptosis sensitivity, suggesting that inhibition of MTDH S-palmitoylation may be a potential strategy for breast cancer therapy." (PMID 41318030, 2025). "It has been shown that MTDH promotes breast cancer metastasis." (PMID 41318030, 2025). "To achieve this, we firstly generated MTDH knockdown breast cancer cell lines by using shRNAs." (PMID 41318030, 2025). "MTDH is overexpressed in multiple cancers, including breast cancer." (PMID 38977630, 2024). "Thus, we confirmed the regulatory relationship of the MTDH/NF-κB (p65)/QPCT axis in breast cancer cells." (PMID 38417050, 2024). "Previous studies have demonstrated that metadherin (MTDH) involves in DOX resistance in breast cancer, but the exact mechanism remains unclear." (PMID 38417050, 2024). "Inhibition of MTDH reduces paclitaxel resistance in breast cancer cells." (PMID 38977630, 2024). "The expression levels of QPCT and MTDH proteins in breast cancer tissues were detected by IHC." (PMID 38417050, 2024). "In breast cancer, MTDH acts as a mediator for numerous non-coding RNAs." (PMID 38977630, 2024). "Breast cancer metastasis and invasion are both promoted by the oncoprotein Metadherin (MTDH)." (PMID 38253625, 2024). "LINC00707 directly targets MTDH to inhibit breast cancer by sponging miR-876." (PMID 38977630, 2024). "Additionally, there exists a correlation between Metadherin, immune infiltration, and survival rates in breast cancer." (PMID 38253625, 2024). "However, the the role of Metadherin in breast cancer progression and its role in the immune microenvironment." (PMID 38253625, 2024). "As a result, we think the MTDH/NF-κB/QPCT axis can affect DOX sensitivity of breast cancer cells." (PMID 38417050, 2024). "Given that numerous metastasis-related gene polymorphisms are known to be associated with an increased risk of breast cancer, the impact of MTDH polymorphisms on breast cancer susceptibility has not yet been reported." (PMID 38977630, 2024). "In broad terms, Metadherin is found to be elevated in tissues affected by breast cancer." (PMID 38253625, 2024). "In addition, TP73-AS1 boosted cell proliferation, invasion, and migration, and functioned as a ceRNA with miR-200a to prevent binding of TFAM, dampening the TP73-AS1/miR-200a/ZEB1 and TP73-AS1/miRNA-125a-3p/ metadherin axis in breast cancer." (PMID 35614413, 2022). "To investigate whether miR-9-3p regulated the sensitivity of breast cancer cells to Gem through targeting MTDH, we examined the effects of low-expressed or overexpressed miR-9-3p and MTDH on migration, invasion, and EMT-related proteins of breast cancer cells." (PMID 34552061, 2021). "siMTDH and MTDH were transfected into breast cancer cells for in vitro experiments, and we explored the effects of MTDH on the sensitivity of mice to Gem by in vivo mouse tumor formation experiments, as we expected, our in vitro and in vivo experiments confirmed the previous results." (PMID 34552061, 2021). "Indeed, we observed that about 1000–3000 genes were differentially expressed in breast cancer cells when the MTDH gene was knocked down, but few genes were altered in endometrial cells according to the knockdown of MTDH." (PMID 33802672, 2021). "In addition, TCGA data analysis showed that the prognosis of breast cancer patients with high-expressed MTDH is poor." (PMID 34552061, 2021).
breast carcinoma (continued). "LINC00707, the miR-876 molecular sponge, modulates MTDH expression within breast cancer." (PMID 34486476, 2021). "We found that MCF7 cells with high-expressed MTDH had the lowest sensitivity to Gem, while HCC1806 cells with low-expressed MTDH showed the highest sensitivity to Gem, suggesting that higher expression of MTDH in breast cancer cells was negatively related to the sensitivity of cells to Gem." (PMID 34552061, 2021). "Berberine exerts anticancer activity partially by regulating MTDH expression in breast cancer." (PMID 35046810, 2021). "Our study suggests that the inhibition of MTDH and IL-10 may have potential with regard to developing new therapeutic strategies for breast cancer." (PMID 33003428, 2020). "MTDH, also called AEG1 and LYRIC, was shown to be involved in the carcinogenesis and progression of various types of tumors, including breast cancer, glioma, hepatocellular carcinoma and squamous cell carcinoma, suggesting that MTDH is a prognostic molecular biomarker and therapeutic target." (PMID 31978894, 2020). "Although some studies have already demonstrated that miR-30a, miR-630, miR-320 and miR-26a can inhibit the expression of MTDH resulting in suppression of breast cancer metastasis, the “miR-128/MTDH” is a newly identified “metastamir-oncogene” pair acting on metastasis in the present work." (PMID 32993809, 2020). "MiRNA-30a inhibits breast cancer proliferation and metastasis by directly targeting MTDH." (PMID 32403384, 2020). "The high expression of MTDH was closely related to the survival rate of breast cancer patients." (PMID 31912882, 2020). "Moreover, analysis of the GEPIA 2 database indicated that the expression of MTDH positively correlates with the level of FAM83H-AS1 in breast cancer tissues." (PMID 32074085, 2020). "Moreover, MTDH enhanced the ability of breast cancer cells to use intracellular glutamate to maintain respiratory chain activity, which has been demonstrated to be an important metabolic process promoting ferroptosis." (PMID 33292585, 2020). "High metadherin gene expression was highly correlated with breast cancer metastasis." (PMID 31737791, 2019). "In contrast, reduction in miR-630 expression results in increased MTDH expression in breast cancer." (PMID 31131259, 2019). "Upregulation of the MTDH gene could promote the proliferation of a variety of tumor cells, such as esophageal cancer, gastric cancer, glioma, and breast cancer." (PMID 30227879, 2018). "We first explored the role of MTDH gene in the TAX therapeutic efficiency toward breast cancer cells and then investigated whether a nanoparticle (NP)-based co-delivery method can be used to address TAX resistance issue in breast cancer treatment." (PMID 30227879, 2018). "The result showed that MTDH was upregulated in breast cancer, especially in TNBC cell lines." (PMID 29088804, 2017). "AEG‐1/MTDH was subsequently found to mediate the metastasis of breast cancer." (PMID 28661037, 2017). "MTDH was initially reported as a protein mediating metastasis of mouse breast cancer." (PMID 29029495, 2017). "Functionally, Dr. Kang’s group recently demonstrated that the interaction of MTDH and Staphylococcal nuclease domain-containing 1 is crucial for expansion and activity of tumor-initiating cells in diverse oncogene- and carcinogen-induced mammary tumors." (PMID 29029495, 2017). "Thus, MTDH has been identified as the mediator of pathological functions of miR-630 in breast cancer cells." (PMID 26595523, 2016). "Our study showed MTDH overexpression in breast cancer predicted poor outcome." (PMID 27229534, 2016). "Therefore, we conclude that miR-320a can suppress MTDH expression and inhibit breast cancer invasion and metastasis in vivo." (PMID 27229534, 2016). "MTDH is typically overexpressed in greater than 40% of breast cancers." (PMID 26917087, 2016).
breast carcinoma (continued). "High immunohistochemical expression of MTDH is remarkably associated with shorter disease-free survival (DFS) in breast cancer but not in ovarian cancer." (PMID 27917902, 2016). "Collectively, these findings suggest that MTDH is a functional target of miR-320a in breast cancer." (PMID 27229534, 2016). "In conclusion, MTDH might be a novel biomarker which can effectively reflect metastasis status and prognosis of breast cancer." (PMID 27917902, 2016). "In conclusion, our data suggest that miR-320a may inhibit invasion and metastasis of breast cancer by downregulating MTDH." (PMID 27229534, 2016). "Moreover, function studies showed that MTDH silencing phenocopied overexpression of miR-320a in breast cancer cells, resulting in migration/invasion suppression." (PMID 27229534, 2016). "The present study provides new insight into anti-oncogenic roles of miR-320a in the breast cancer pathogenesis and suggests that miR-320a/MTDH pathway could be a putative therapeutic target in breast cancer." (PMID 27229534, 2016). "Furthermore we identify a multifaceted oncogene, MTDH, as the direct target of miR-630 in breast cancer cells." (PMID 26595523, 2016). "Moreover, we found that MTDH was negatively correlated with miR-320a expression, and it was related to clinical outcomes of breast cancer." (PMID 27229534, 2016). "For breast cancer, the results of our meta-analysis implied that MTDH might be a novel biomarker being applied to clinic." (PMID 27917902, 2016). "Furthermore, in the present study, we would attempt to identify a drug, or an approach that can reverse the clinical resistance of breast cancer cells to doxorubicin through inhibiting MTDH gene." (PMID 25993398, 2015). "Therefore, the higher MTDH-expressed breast cancer cell line displayed the more resistance to doxorubicin." (PMID 25993398, 2015). "The treatment of tamoxifen-resistant breast cancer may be aided by the development of potential therapeutic approaches, such as the re-expression of miR-375 or the targeting of AEG-1/MTDH." (PMID 25009642, 2014). "MTDH overexpression confers trastuzumab resistance in HER2 positive breast cancer patients, which may also be a potential predictive factor for the evaluation of clinical response to trastuzumab-based anticancer therapy." (PMID 25417825, 2014). "Silencing AEG-1/MTDH expression by RNA interference was found to effectively reduce metastasis by 3- to 10-fold in a MDA-MB-231 xenograft model of breast cancer lung metastasis, and it was also shown to sensitize chemoresistant MDA-MB-231 breast tumors to paclitaxel or doxorubicin." (PMID 25009642, 2014). "Athymic nude mice bearing breast cancer xenografts were used to demonstrate whether MTDH-mediated PTEN silence still exerted a pivotal role in trastuzumab resistance in vivo." (PMID 25417825, 2014). "In addition, miR-375 that directly inhibited MTDH expression reversed both tamoxifen resistance and accompanying epithelial-mesenchymal transition like properties in tamxifen resistant breast cancer cells." (PMID 25417825, 2014). "Given that PTEN is involved in both tamoxifen-resistance and trastuzumab-resistance, more studies are needed to validate whether MTDH is a general or a specific mechanism of drug resistance and how it functions in breast cancer." (PMID 25417825, 2014). "In MDA-MB231 human breast cancer cells, exposure to cadmium chloride affects AEG-1/MTDH expression." (PMID 25009642, 2014). "Since metadherin (MTDH) promotes malignant phenotype of breast cancer, we sought to define whether MTDH promotes trastuzumab resistance by decreasing PTEN expression through an NFκB-dependent pathway." (PMID 25417825, 2014). "In breast cancer cells, AEG-1/MTDH-miRNA may be important in the downregulation of proliferation, motility and migration, and must be used as a future potential small molecule inhibitor therapeutic targeting strategy." (PMID 25009642, 2014).
breast carcinoma (continued). "MTDH overexpression confers trastuzumab resistance in HER2 positive breast cancer." (PMID 25417825, 2014). "In malignant glioma cells, AEG-1/MTDH regulates invasion and migration through activation of the NF-κB signaling pathway, in which AEG-1/MTDH is involved in the lipopolysaccharide (LPS)-induced inflammatory response and mediates the LPS-induced migration and invasion of breast cancer cells." (PMID 25009642, 2014). "AEG-1/MTDH has a dual function in promoting chemoresistance and metastasis, and is a key functional target of the 8q22 genomic gain that is frequently observed in breast cancer patients with a poor prognosis." (PMID 25009642, 2014). "The expression of MTDH gene positively correlated with the clinical stage of breast cancer, prompting that MTDH gene expression may be considered as an independent prognostic indicator for breast cancer." (PMID 23984913, 2013). "The relationship between MTDH and TLR4 signaling pathway might lead to the development of TLR4 and MTDH as novel therapeutic targets for breast cancer." (PMID 22195048, 2011). "Here we report the role of MTDH in promoting invasion and metastasis in breast cancers." (PMID 22195048, 2011). "Here, our study provided the evidence that LPS could upregulate the expression of MTDH which increases the invasiveness of breast cancer." (PMID 22195048, 2011). "So in the proliferative lesions and cancer of breast, MTDH might play an important role, but the exact mechanism is still unknown and need more studies to demonstrate it." (PMID 20565850, 2010). "MTDH overexpression could be identified in proliferative breast lesions and may contribute to breast cancer progression." (PMID 20565850, 2010). "MTDH is overexpressed in highly proliferative lesions of breast cancer and DCIS." (PMID 20565850, 2010). "DTL, ECT2, MTDH, PRC1 and RFC4 have all been previously implicated in breast cancer; SCUBE2 and STK32B deletions have been found to be related to mental deficits in humans; and ZNF533 has been found to be associated with the Hedgehog signaling pathway in Zebrafish." (PMID 20584321, 2010). "Thus, our results suggest that QPCT regulated by the MTDH/NF-κB (p65) axis could affect DOX sensitivity of breast cancer cells." (PMID 38417050, 2024). "Moreover, suppressing MTDH activity hinders the metastatic potential of breast cancer cells." (PMID 38977630, 2024). "Furthermore, anti-cancer agents can target MTDH to suppress breast cancer." (PMID 38977630, 2024). "Because Metadherin expression is elevated in breast cancer tissues and is strongly correlated with immune micro-relationships, the detection of Metadherin in breast cancer tissues may be useful for prognostic speculation or for decision-making regarding immunotherapy." (PMID 38253625, 2024). "In addition, interaction of Snd1 with the RNA‐binding protein Metadherin (MTDH) was shown to be critical for early‐stage tumorigenesis in oncogene and carcinogen‐induced mammary tumor models where Snd1 stabilized the expression of pro‐survival genes under stress conditions." (PMID 37151849, 2023). "The Huaier polysaccharide component SP1 (a type of purified Huaier polysaccharide) could increase the proportion of Bax/Bcl-2 through the MTDH signaling pathway, which could be another potential mechanism of Huaier in apoptosis induction in breast cancer cells." (PMID 35458475, 2022). "Currently, the present study was the first to report that miR-9-3p could bind to MTDH to regulate the pathogenesis of breast cancer, and that there is a shared mechanism through which miR-9-3p and MTDH jointly regulate chemoresistance of breast cancer patients." (PMID 34552061, 2021). "Thus, breast cancer metastasis partially attributes to the miR-128/MTDH axis." (PMID 32993809, 2020). "Recent studies have shown that MTDH could promote lung metastasis of breast cancer." (PMID 33312941, 2020).